CD68 (CD68 molecule)
Diseases named in the same sentence as CD68 in open-access papers (continued):
Sharing a sentence is not in itself a finding about the gene and the disease.
diabetic retinopathy (1 paper, 2022). "Additionally, inflammatory cytokines (TNF-α, IL-1β, and IL-6) produced by CD68-expressing macrophages recruit inflammatory immune cells in the retinas of diabetic animals, crucially contributing to the development and progression of diabetic retinopathy." (PMID 36362313, 2022).
diarrhoea (1 paper, 2022). "Some of the DEGs in diarrhoea-susceptible sheep, enriched in GO terms and sub-network analysis, included IL-6, LOC101121216 (serum amyloid A), SIGLEC1, CHI3L1, S100A9, CD14, CD68, CD86, Ovar-DRB1, IL1RL1, LOC101103238 (CXCL5), CCL22 and IL1RN." (PMID 35576023, 2022).
diffuse astrocytoma (1 paper, 2019). A low-grade (WHO grade II) astrocytic neoplasm. "Comparing diffuse astrocytomas of WHO grade II–IV with pilocytic astrocytomas, both pan‐M/M markers Iba1 and CD68 as well as the presumed M2‐marker C163 were found in significantly higher levels in pilocytic astrocytomas WHO grade I." (PMID 30506802, 2019).
Duchenne muscular dystrophy (1 paper, 2018). Duchenne muscular dystrophy (DMD) is a neuromuscular disease characterized by rapidly progressive muscle weakness and wasting due to degeneration of skeletal, smooth and cardiac muscle. "We found that CD140a-expressing FAPs were located close to CD68 positive macrophages in muscles from patients with Duchenne muscular dystrophy (DMD)." (PMID 30451963, 2018).
Dyskinesia (1 paper, 2022). A movement disorder which consists of effects including diminished voluntary movements and the presence of involuntary movements. "A strong positive correlation (r = 0.673, p = 0.008) was also observed between the mean dyskinesia score and CD68 levels in the putamen at the pre-commissural level." (PMID 35203338, 2022). "The present study investigated levels of microglia (Iba1 and CD68) and astrocytes (GFAP) markers of inflammation and gliosis in the brain of MPTP monkeys with different levels of dyskinesias induced by L-Dopa and prevented with an added treatment with MPEP a NAM of mGlu5 receptor." (PMID 35203338, 2022).
echinococcosis (1 paper, 2021). A parasitic infection caused by tapeworm larvae of Echinococcus. "A patient with a liver abscess (D27) showed a larger number of CD68+ cells without an inflammatory state compared to the donor with echinococcosis (D18) but also the largest proportion of pro-inflammatory cells in the FACS analysis." (PMID 33918803, 2021).
embryonal carcinoma (1 paper, 2024). A non-seminomatous malignant germ cell tumor characterized by the presence of large germ cells with abundant cytoplasm resembling epithelial cells, geographic necrosis, high mitotic activity, and pseudoglandular and pseudopapillary structures formation. "Except for CD68+ macrophages, infiltration densities of all immune cell types in embryonal carcinoma were statistically significant compared to NSP." (PMID 38649788, 2024).
encephalomyelitis (1 paper, 2015). Inflammation of the brain and the spinal cord. "It was compared qualitatively and quantitatively to Iba1 and CD68 immunohistochemical staining in two models: rat spinal cord injury and mouse encephalomyelitis." (PMID 26355949, 2015).
endometritis (1 paper, 2025). An acute or chronic, usually bacterial infectious process affecting the endometrium. "In addition, the profile of CD68+ cells in the total cohort of endometrial cells increased with the severity of endometritis." (PMID 41511322, 2025). "The increase in CD68 may indicate a more active MC participation in infection-induced endometritis in the processing or presentation of an antigen for subsequent immunogenesis." (PMID 41511322, 2025). "The largest pool of MCs immunopositive to CD68 was formed in severe endometritis." (PMID 41511322, 2025).
enteropathy (1 paper, 2013). "In only a few cases of severe enteropathy, macrophages HAM56+ cells (Figure 4Avi) or CD68+ cells (not shown) exhibited MICA/B expression." (PMID 24058482, 2013).
epulis (1 paper, 2023). A non-neoplastic nodular lesion that arises from the gingiva. "In the case of fibroid epulis, there are no data regarding the immunoreactivity of GCs for CD68." (PMID 37509363, 2023).
esophageal tumors (1 paper, 2020). "The number of PU.1+ macrophages strongly correlates with the number of CD68+ macrophages; therefore, usage of PU.1 as a potential macrophage marker can be recommended for esophageal tumors." (PMID 32884895, 2020). "We performed a correlation analysis of various macrophage markers in esophageal tumor and demonstrated that PU.1 expression strongly correlates with that of CD68 (r = 0.833, p ≤ 0.001), CD163 (r = 0.500, p ≤ 0.001), and CD206 (r = 0.250, p = 0.043) with the strongest correlation observed for CD68." (PMID 32884895, 2020).
esophagitis (1 paper, 2015). An acute or chronic inflammatory disease affecting the esophageal wall. "In the distal esophagus lesion, stromal macrophages (immunoreactive for CD68) were more commonly found in pill-induced esophagitis than in reflux esophagitis, while intraepithelial mast cells (immunoreactive for CD117) were more frequent in reflux esophagitis (P < 0.05)." (PMID 26047496, 2015).
fibroma (1 paper, 2023). A non-metastasizing neoplasm arising from the fibrous tissue. "For the GCs in non-ossifying fibroma, there are no data with regard to CD68-immunoreactivity." (PMID 37509363, 2023).
gallbladder cancer (1 paper, 2024). "The expression levels of CD68 and CD163 in M2-like TAMs and CD44 and CD133 in gallbladder cancer stem cells (GBCSCs) were increased and positively correlated in GBC tissues compared with those in neighboring noncancerous tissues." (PMID 39138521, 2024).
gastrointestinal stromal tumor (1 paper, 2026). "Histopathological examination with immunohistochemical staining (CD8+, CD68+, CD117-, DOG1-) confirmed the diagnosis of splenosis and excluded malignancies such as gastrointestinal stromal tumor (GIST) and carcinoma." (PMID 41982241, 2026).
giant cell tumor (1 paper, 2010). A benign, intermediate, or malignant tumor that arises from the bone or soft tissue. "In karyotypic analysis of giant cell tumors of bone, end-to-end fusions of various chromosomes, termed telomeric associations, are seen in most tumors in a subset of cells, and these have been localized by FISH studies to the CD68 negative spindled stromal component." (PMID 20860830, 2010).
Glucose intolerance (1 paper, 2023). Glucose intolerance (GI) can be defined as dysglycemia that comprises both prediabetes and diabetes. "C57BL/6J mice displayed a glucose intolerance profile and CD68+ cell infiltration in the AT, whereas adipocyte hypertrophy and enhanced inflammatory cells − both CD68+ and MC − density were prominent in the BALB/c strain." (PMID 36829849, 2023).
goiter (1 paper, 2025). Enlargement of the thyroid gland usually caused by lack of iodine in the diet, hyperthyroidism, or thyroid nodules. "We have further assessed PTX3 and CD68 expression by immunohistochemistry in tissue samples from 2 patients with goiter, 1 patient with papillary TC (PTC), and 4 patients with ATC." (PMID 41373493, 2025). "There was a higher number of infiltrating CD68-positive cells in ATC compared with the PTC and goiter samples." (PMID 41373493, 2025). "However, immunohistochemically, PTX3 and CD68 staining were virtually absent in patients with goiter, and in those with PTC." (PMID 41373493, 2025).
graft versus host disease (1 paper, 2025). An immune system disorder that occurs after allogeneic hematopoietic stem cell transplant and is a reaction of donor immune cells against host tissues. "Multiplex immunohistochemistry revealed increased numbers of S1PR2+CD45+CD68+FCN1+ inflammatory macrophages and S1PR2+CD45+CD68+MARCO+ Kupffer cells in liver tissues showing ductopenia due to graft-versus-host disease and rejection post-liver transplant compared with normal liver." (PMID 39854311, 2025).
Gynecomastia (1 paper, 2023). Abnormal development of large mammary glands in males resulting in breast enlargement. "In the two patients in which CD68+/Cd1a(-) histiocytes were found in the breast, the gynecomastia was described to have been onset since the age of 50, with a progressive development of severe gynecomastia during the VI decade of life." (PMID 37046457, 2023).
HCMV infection (1 paper, 2013). "In addition, we sought to determine whether HCMV infection was associated with inflammatory activity in the plaque by quantifying infiltrating CD3 and CD68 positive cells and 5-LO immunoreactivity." (PMID 24229441, 2013).
heart tumors (1 paper, 2023). "Immunohistochemical analysis with antibodies against CD34 and CD68 was also conducted on the same 11 Post-COVID period heart tumors." (PMID 37895467, 2023).
HELLP syndrome (1 paper, 2023). A life-threatening condition that can potentially complicate pregnancy. "Pathology of the HELLP syndrome is in relation to CD68-positive placental macrophages." (PMID 37899759, 2023).
hemorrhagic stroke (1 paper, 2023). A stroke caused by a bleed on the brain. "In hemorrhagic stroke, rhCDNF treatment did not increase the density of ARG1-positive cells, but rather modestly decreased the density of CD68-positive cells in the lateral peri-hematoma striatum." (PMID 36792604, 2023).
hepatic granuloma (1 paper, 2015). A granuloma located in the liver. "Merge in white were demonstrated co-expression of IL-13Rα2 and CD68 at the same position of egg-induced hepatic granuloma (white)." (PMID 26317423, 2015).
hepatitis C (1 paper, 2018). "CD68 was detected in the inflammatory infiltrate in all cases of recurrent hepatitis C and ACR and was localized in portal tracts and adjacent parenchyma." (PMID 29854831, 2018). "In this study, CD68 was expressed in all cases of recurrent hepatitis C and ACR, indicating the presence of macrophage infiltration of portal tracts in both groups." (PMID 29854831, 2018). "Twelve cases (46.2%) of recurrent hepatitis C showed high expression of CD68 in comparison to 17 patients (65.4%) in ACR." (PMID 29854831, 2018).
Hyperammonemia (1 paper, 2020). An increased concentration of ammonia in the blood. "Microglial activation was also analyzed by assessing the effects of hyperammonemia on CD68, a specific marker of activated microglia." (PMID 32087723, 2020). "Hyperammonemia strongly increased (p < 0.0001) the number of cells stained with CD68 in the white matter to 11 ± 2 cells/mm2 compared to 4 ± 1 cells/mm2 in control rats." (PMID 32087723, 2020).
Hypokalemia (1 paper, 2018). An abnormally decreased potassium concentration in the blood. "There were more CD163 and CD68 positive cells infiltration in tubulointerstitial injury of pSS, especially in patients with hypokalemia." (PMID 30396309, 2018).
hypothyroidism (1 paper, 2017). Abnormally low levels of thyroid hormone. "In addition, hypothyroidism induced hypertrophy of adipocytes and a major infiltration of CD68+ macrophages into the periovarian VAT." (PMID 28133606, 2017).
ileus (1 paper, 2019). Decrease in peristalsis in the absence of a mechanical bowel obstruction. "Administration with 5-HT4R agonists significantly reduced the number of infiltrated CD68-positive macrophages and MPO-stained neutrophils in the intestine of mice with postoperative ileus, and this was in agreement with previous results observed in rat models." (PMID 30971711, 2019).
impaired spermatogenesis (1 paper, 2022). "Furthermore, analysis of testicular biopsies from patients with impaired spermatogenesis, testicular fibrosis, and inflammation showed that fibronectin expression was increased in CD68+ macrophages." (PMID 36434305, 2022).
Intestinal inflammation (1 paper, 2023). "Intestinal inflammation was characterized by the numbers of CD3+ duodenal intraepithelial lymphocytes (IELs), CD68+ macrophages, and villi structures in different study groups." (PMID 37304826, 2023).
intrauterine growth restriction (1 paper, 2024). "CD68+ macrophages in the placenta are associated with intrauterine growth restriction in humans and secretion of proinflammatory cytokines." (PMID 38190129, 2024).
iron metabolism disorder (1 paper, 2023). "In macrophages, the up-regulation of Cav-1 promoted the expression of HO-1 in CD68+CD163+ macrophages, which facilitated the degradation of red blood cells into Fe2+ within macrophages and accelerated iron metabolism disorder in NAFLD." (PMID 37941054, 2023).
ischemic cardiomyopathies (1 paper, 2021). "However, as it was shown that the majority of heart resident human CD68+ macrophages co-express CD14 in dilated and ischemic cardiomyopathies, we applied CD86 and CD163 as additional markers for M1 and M2 macrophages, respectively." (PMID 33432417, 2021).
juvenile dermatomyositis (1 paper, 2024). Juvenile dermatomyositis (JDM) is the early-onset form of dermatomyositis (DM), a systemic, autoimmune inflammatory muscle disorder, characterized by proximal muscle weakness, evocative skin lesion, and systemic manifestations. "An innate immune signature was also unveiled when comparing JDM (juvenile dermatomyositis) skin biopsies to cutaneous lupus, (CLE), with an elevated expression of CD68+ and CD14+ macrophages." (PMID 39896815, 2024).
keratitis (1 paper, 2014). A corneal disease that is characterized by inflammation of the cornea. "Stromal infiltration of CD68+ve positive cells was seen in both herpetic and gram-negative keratitis sections, associated with TLR3 and TLR4 expression in the corneal epithelium, respectively." (PMID 24736562, 2014).
kidney cancer (1 paper, 2021). Primary or metastatic malignant neoplasm involving the kidney. "Therefore, we used ten fresh kidney cancer tissues to perform real-time fluorescent quantitative PCR experiments to detect the correlation between SOD2, CAT, and the macrophage marker CD68." (PMID 34721758, 2021).
kidney injury (1 paper, 2023). Trauma to the kidney. "Expression of ISGs (Mx1, Isg15, Isg20, Ifitm1, Bst2, and Oas1), and immune cell markers Lyz2 and Cd68 were markedly lower in 3TC mice with FA-induced kidney injury compared to controls." (PMID 36732547, 2023).
kidney transplant (1 paper, 2021). A surgical procedure in which one or both kidneys from a donor are implanted into a recipient. "While the observed trend was consistent with published data, we could not confirm the detrimental effect of early presence of CD68+ macrophages that has been previously reported for other kidney transplant patient groups." (PMID 34006891, 2021).
kidney tumor (1 paper, 2016). "To investigate the potential linkage or impacts of infiltrating macrophages, the major immune cells existing in the kidney tumor microenvironment, in RCC progression, we applied IHC with anti-CD68 antibody, a specific marker of macrophages in human RCC and surrounding non-tumor tissues." (PMID 27283897, 2016).
Krabbe disease (1 paper, 2021). A lysosomal disorder that affects the white matter of the central and peripheral nervous systems. "Indeed, the contribution of microglia to the pathology of these leukodystrophies is supported by findings in patient postmortem brain tissue, in which CD68+ phagocytic microglia are abundant in both the affected and least-affected white matter of Krabbe disease, MLD and X-ALD patient brain tissue." (PMID 34282843, 2021).
laryngeal squamous cell carcinoma (1 paper, 2022). A squamous cell carcinoma that arises from the larynx. "In laryngeal squamous cell carcinoma (LSCC), CD68+ cells were involved in angiogenesis and correlated with worse prognosis." (PMID 36686729, 2022).
laryngeal tumors (1 paper, 2018). "The density of CD68+ macrophages was significantly higher in the stroma of laryngeal tumors than in the stromal compartment of hypopharyngeal and oropharyngeal carcinomas." (PMID 29541395, 2018).
Leber congenital amaurosis (1 paper, 2016). Leber congenital amaurosis (LCA) is a retinal dystrophy defined by blindness and responses to electrophysiological stimulation (Ganzfeld electroretinogram (ERG)) below threshold, associated with severe visual impairment within the first year of life. "Immunohistochemical assays of the epithelial membrane antigen (EMA), S100, vimentin, KI67, creatine kinase (CK), Leber congenital amaurosis (LCA), CD68, antibodies against glial fibrillary acidic protein (GFAP), BCL2, anaplastic lymphoma kinase (ALK), and synaptophysin levels were performed." (PMID 27917338, 2016).
leishmaniasis (1 paper, 2021). Infectious disease that is transmitted through the bite of hematophagous female phlebotomine sand flies. "The current study showed that CD1a epidermal, dermal DCs, and CD68 macrophages are the most important cells that regulate the outcome of leishmaniasis." (PMID 33507940, 2021).
Lewy body disease (1 paper, 2026). "Lewy body disease patients exhibited increased HLA-DR and CD68 in most hippocampal subfields compared with primary age-related tauopathy." (PMID 41726931, 2026).
lipodystrophy (1 paper, 2024). A congenital or acquired disorder characterized by abnormal loss or redistribution of the adipose tissue in the body. "Furthermore, AT inhibited lipodystrophy-associated increase of plaque macrophage infiltration and aortic expression of proinflammatory cytokines (Mcp-1, Il-1β, and Il-6) in Seipin/Apoe dKO mice, as shown by CD68 immunohistochemical staining and real-time quantitative PCR analysis, respectively." (PMID 38525541, 2024).
lipoma (1 paper, 2025). A benign, usually painless, well-circumscribed lipomatous tumor composed of adipose tissue. "On microscopy, they are defined by aggregates of foamy histiocytes positive for CD68 and negative for S100, helping to exclude mimics such as lipomas, mucosal prolapse, and signet-ring cell carcinoma." (PMID 40693216, 2025).
liver cirrhosis (1 paper, 2023). "Cd68 is highly expressed in the entire stage of NASH-liver cirrhosis-HCC, reflecting key roles of macrophages." (PMID 37509405, 2023).
localized scleroderma (1 paper, 2024). Localized scleroderma is the skin localized form of scleroderma characterized by fibrosis of the skin causing cutaneous plaques or strips. "Here, immunofluorescence was performed to examine TREM2+ MФs alteration in human skin lesions of diffuse cutaneous SSc (dcSSC) and localized scleroderma (LS), and found that there was a dramatic upregulation of CD68+TREM2+ MФs during skin fibrosis progression." (PMID 38505612, 2024).
low grade glioma (1 paper, 2021). A grade I or grade II glioma arising from the central nervous system. "In low-grade glioma, the number of CD68+ (a marker of M2) cells is positively associated with malignancy degree and is inversely related to the recurrence-free survival." (PMID 34446611, 2021).
lung tumor (1 paper, 2016). "This may be partially due to the reverse prognostic impacts of CD68+ TAMs in lung tumor islet and stroma." (PMID 27144518, 2016).
Lyme borreliosis (1 paper, 2006). "The inflammatory infiltrate in both the early and late skin manifestations of Lyme borreliosis is mainly composed of CD68+ macrophages and CD45RO+ memory T cells, with a predominance of CD4+ helper T cells." (PMID 16495924, 2006).
Lynch syndrome (1 paper, 2021). An autosomal dominant hereditary neoplastic syndrome characterized by the development of colorectal carcinoma and a high risk of developing endometrial carcinoma, gastric carcinoma, ovarian carcinoma, renal pelvis carcinoma, and small intestinal carcinoma. "Our results showing a favorable prognosis in younger patients with a high number of intratumoral CD68+CLEVER-1+ TAMs may be linked with hereditary Lynch syndrome, which is characterized by mutations in the MMR genes leading to MSI-H tumors." (PMID 34885098, 2021).
Lysosomal disease (1 paper, 2009). "Neuro-inflammation is also an important component of many lysosomal diseases, and upon IHC staining of CD68, a CNS inflammatory marker, we noted reduced labeling in brains of end-stage CD-treated Npc1−/− mice compared to end-stage untreated Npc1−/− mice (data not shown)." (PMID 19750228, 2009).